TNFSF14 (TNF superfamily member 14)
Diseases named in the same sentence as TNFSF14 in open-access papers (continued):
Sharing a sentence is not in itself a finding about the gene and the disease.
breast carcinoma (12 papers, 2013 to 2024). "For DDX10 there is one paper which co-cites DDX10 and one of its 11 predicted targets, TNFSF14, in a study of changes in hormone receptor target genes and chromatin modifying enzymes after proteasome inhibition in breast cancer cells." (PMID 25148247, 2014). "MSC secrete high amounts of cytokines, which induce the inhibition of tumor growth in vivo in breast cancer cells such as IL12, IFN-α, CXCL10, LAP, DKK-1/3, TRAIL, TNFSF14 (also known as LIGHT), and FLT-3 ligand." (PMID 36421393, 2022). "MSC produce high level of cytokines, such as IFN-α, DKK-1/3, IL12, TRAIL, TNFSF14 (also known as LIGHT), FLT-3 ligand, CXCL10 and LAP, known to inhibit tumor growth in vivo in breast cancer cells." (PMID 36012170, 2022). "It has been shown that MSC secrete high amounts of cytokines, which induce inhibition of tumor growth in vivo in breast cancer cells, such as IFN-α, DKK-1/3, IL12, TRAIL, TNFSF14 (also known as LIGHT), FLT-3 ligand, CXCL10, and LAP." (PMID 33808241, 2021). "LIGHT, also termed tumor necrosis factor superfamily member 14 (TNFSF14), has been widely reported in a range of malignancies, including non-small-cell lung cancer (NSCLC), multiple myeloma, colorectal cancer, prostate tumor, breast cancer, and melanoma (Hehlgans and Männel, 2001)." (PMID 34513918, 2021). "One of its ligands, LIGHT, otherwise known as tumor necrosis factor superfamily member 14 (TNFSF14) or CD258, could improve the effect of immunotherapy in multiple cancer models, such as lung carcinoma, breast carcinoma, cervical cancer, prostate cancer and GBM." (PMID 36341396, 2022).
Sepsis (11 papers, 2020 to 2026). Sepsis is defined as life-threatening organ dysfunction caused by a dysregulated host response to infection. "Previous studies on severe viral pneumonia and sepsis positively linked elevated BALF/serum TNFSF14 levels to disease severity." (PMID 41252214, 2026). "For instance, TNFSF14 exacerbated sepsis‐related acute kidney injury via the TLR4/MyD88/NF‐κB pathway and activated the NFκB‐TLR3 pathway to induce acute hepatitis." (PMID 40768619, 2025). "Collectively, these results pinpoint NFKBIA, NFKB2, TNFSF14, DUSP2, and PIK3C2B as key mediators of DcR3’s broad-spectrum effects in CLP-induced sepsis." (PMID 38700314, 2024).
atherosclerosis (10 papers, 2013 to 2025). A disease characterized by the build-up of fatty material and calcium deposition in the arterial wall resulting in partial or complete occlusion of the arterial lumen. "TNFSF14 is involved in atherosclerosis and vascular inflammation." (PMID 41272580, 2025). "TNFSF14 is a transmembrane protein belonging to the tumor necrosis factor (TNF) ligand family, which may have a pathogenic function in atherosclerosis." (PMID 36676179, 2023). "Here, we present data indicating that many atherosclerosis and cardiovascular risk-related proteins that were found to be up-regulated in other Olink studies (e.g., SELE/E-selectin, TNFSF14/LIGHT, VEGFA, RETN/resistin, MMPs) are in fact suppressed by dupilumab in tape-stripped skin lesions." (PMID 32849633, 2020).
diabetes (10 papers, 2016 to 2026). "Collectively, these findings suggest that PET microplastics may increase the risk of β-cell damage and contribute to the development of diabetes by upregulating key cytokines such as IL-12β, TNFSF3, TNFSF14 and TNFRSF18." (PMID 40597598, 2025). "On the basis of its role in vascular inflammation and in metabolic disorders, we hypothesised that the TNF superfamily (TNFSF) member 14 (LIGHT/TNFSF14) could be involved in the pathogenesis of type 2 diabetes mellitus." (PMID 27421726, 2016).
glioblastoma (10 papers, 2019 to 2025). The most malignant astrocytic tumor (WHO grade IV). "In our model, the genes TNFRSF14 and TNFSF14 are also associated with a poorer prognosis in glioblastoma through complex interaction networks." (PMID 38365809, 2024). "The evidence presented suggests a potential correlation between TNFRSF14 and TNFSF14 with poorer prognosis in glioblastoma." (PMID 38365809, 2024). "Similar associations were observed in the CGGA-glioblastoma cohort for CD40, CD276, TNFRSF14, and TNFSF14, except for TNFSF4 and TNFRSF18." (PMID 38365809, 2024). "Based on these findings, we established a risk signature comprised of CD276, TNFRSF14, TNFSF14, TNFSF4, CD40, and TNFRSF18 to predict OS and response to immune checkpoint blockade in glioblastoma patients." (PMID 38365809, 2024). "In glioblastoma, TNFSF14 is involved in T cell activity and inflammatory processes, which can indicate patient prognosis and immunotherapy efficacy." (PMID 38720884, 2024). "Specific targeting of LIGHT/TNFSF14 to tumor vessels using vascular targeting peptides improved vessel functionality, activated endothelial cells and induced formation of HEV in murine glioblastoma, associated with enhanced accumulation of lymphocytes." (PMID 31690961, 2020). "In addition, we obtained representative IHC staining images of CD276, TNFSF4, TNFRSF14, CD40, TNFSF14, and TNFRSF18 in both normal tissues and glioblastoma samples from the Human Proteome Atlas." (PMID 38365809, 2024).
melanoma (9 papers, 2013 to 2026). A malignant, usually aggressive tumor composed of atypical, neoplastic melanocytes. "Finally, eight genes (GPR87, KIT, SH3GL3, PVRL1, ATP1B1, CDAN1, FAU, and TNFSF14) were identified to be closely associated with the OS in melanoma." (PMID 32411243, 2020). "In our study, we identified two gene expression patterns and generated an 8-gene-based (GPR87, KIT, SH3GL3, PVRL1, ATP1B1, CDAN1, FAU, and TNFSF14) gene signature that could recognize melanoma patients with a high risk of unfavorable clinical outcomes." (PMID 32411243, 2020). "KIT, which is a famous oncogene, is often mutated in advanced melanoma and contributes to malignancy progression and an unfavorable prognosis, while highly expressed TNFSF14 in human melanoma cells and microvesicles may contribute to the mediation of T cell responses to cancer cells." (PMID 32411243, 2020). "Our ligand-receptor-based cell communication analysis demonstrated increased interactions between ETV4-low melanoma cells and T cells, including TNFSF14-LTBR and IFNG-(IFNGR1+IFNGR2) signaling pathways." (PMID 41502516, 2025). "The expression of TNFSF14 in melanoma cells contributes to regulate T-cell responses to tumor cells." (PMID 33329712, 2020). "All eligible gene sets were analyzed, and the 8 genes (GPR87, KIT, SH3GL3, PVRL1, ATP1B1, CDAN1, FAU, and TNFSF14) with the greatest prognostic impact on melanoma." (PMID 32411243, 2020). "We identified an 8-gene signature (i.e., GPR87, KIT, SH3GL3, PVRL1, ATP1B1, CDAN1, FAU, and TNFSF14) with independent prognostic value on melanoma." (PMID 32411243, 2020). "Notably, STAT1 was involved exclusively in Stage 4–specific synergistic relationships within the melanoma network, whereas TNFSF14, STK17B, SAMD3, PLAC8, and LYN were all Stage 1–specific synergistic genes that synergized with FENDRR." (PMID 40728857, 2025). "Our signature consists of diverse genes comprising protective (ATP1B1, CDAN1, FAU, and TNFSF14)) and risky (GPR87, KIT, SH3GL3, and PVRL1), which could be considered gene-related protective and risk patterns in melanoma." (PMID 32411243, 2020).
multiple myeloma (9 papers, 2014 to 2025). "It has been reported that CD200, TMIGD2 and TNFSF14 can facilitate anti-tumor immune responses by enhancing T and NK cell activity in multiple myeloma and hematologic malignancies." (PMID 40342824, 2025).
multiple sclerosis (9 papers, 2016 to 2024). A progressive autoimmune disorder affecting the central nervous system resulting in demyelination. "The TRIP10 and GPR108 promoters were each captured in contact with a high-confidence variant rs1077667 (PP > 0.99), which is located in an intron of TNFSF14 and is associated with multiple sclerosis." (PMID 39302339, 2024). "TNFSF14 has been identified as a risk gene for multiple sclerosis however, little is known about its affects in TBI and further investigation of this relationship is required." (PMID 32059364, 2020). "For example, the multiple sclerosis (MS) protective allele near the co-stimulatory ligand LIGHT (encoded by TNFSF14) was associated with increased expression of this molecule in monocytes." (PMID 27435189, 2016). "This study presented a list of bioactive compounds with suitable binding affinity over the DNAJB1 and TNFSF14 as the cutpoint proteins in the multiple sclerosis network based on a molecular docking survey." (PMID 35676653, 2022). "The maximum reduction of Dnajb1/Dnajb2/Foxp1/Tnfsf14 network was observed when Multiple sclerosis rats were treated with exercise training and 100 mg/kg Royal jelly (ET-RJ100), but the relative expression of the Hspa4 significantly increased." (PMID 35676653, 2022). "The maximum reduction of the Dnajb1/Dnajb2/Foxp1/Tnfsf14 network was observed when Multiple sclerosis rats were treated with exercise training and 100 mg/kg Royal jelly (ET-RJ100), but the relative expression of the Hspa4 significantly increased." (PMID 35676653, 2022). "Soluble TNFSF14 may serve a protective role in multiple sclerosis, play a critical role in limiting disease progression and inflammation during experimental autoimmune encephalomyelitis and intestinal inflammation." (PMID 34638990, 2021).
viral infections (8 papers, 2013 to 2026). "TNFSF14 associates with viral infections other than influenza, so interrupting TNFSF14/LTβR signaling may have broader applicability for preventing bacterial superinfections secondary to respiratory viruses." (PMID 41542776, 2026). "Notably, CD4+ T-cells in severe patients showed lower expression of the TNF superfamily ligands TNFSF10 (TRAIL) and TNFSF14 (LIGHT) and the surface protein SLAMF1 and KLRB1, all of which have roles in viral infections." (PMID 33178221, 2020).
Autoimmunity (7 papers, 2019 to 2024). The occurrence of an immune reaction against the organism's own cells or tissues. "The 2nd top biomarker, TNFSF14 (also known as LIGHT), promotes the differentiation of various inflammatory cells and IL-6 production, inhibits T cell activation, and reduces Th1 chemokine expression in other autoimmune disorders." (PMID 39165841, 2024).
pancreatic cancer (7 papers, 2013 to 2024). "The MYXV, carrying the LIGHT (TNFSF14) gene, was pre-loaded into adipose-derived mesenchymal stem cells (ADSCs) and utilized for the treatment of pancreatic cancer in mice." (PMID 39055561, 2024).
colon carcinoma (6 papers, 2017 to 2023). "Maker and co-workers have shown that increased expression of TNFSF14 enhances the activity of cytotoxic T-lymphocytes and thereby mediates immune eradication of colon cancer metastases." (PMID 30987352, 2019). "Finally, a recent study reported that TNFSF14 promotes tumour-specific anti-tumour immunity and thus has potential as an immunotherapeutic agent to treat colon cancer and liver cancer." (PMID 34638990, 2021). "TNFSF14-LTBR pathway plays a vital role in immune responses in the TME of many types of cancer, but this pathway has not been reported in TME of colon cancer, suggesting it might be an important immunotherapeutic target for CRC treatment." (PMID 35910200, 2022).
pneumonia (6 papers, 2019 to 2026). An acute, acute and chronic, or chronic inflammation focally or diffusely affecting the lung parenchyma, caused by an infection in one or both of the lungs (by bacteria, viruses, fungi, or mycoplasma.). "Given that severe HAdV-55 infection also causes pneumonia, it is likely that TNFSF14 participates in the HAdV-55-induced inflammation in lungs." (PMID 30787914, 2019). "Moreover, the herpes virus entry mediator, which is the receptor of TNFSF14, is linked to dysregulated mucosal function such as pneumonia." (PMID 30787914, 2019). "For mice exposed to chronic cigarette smoke, a soluble LTβR protein that inhibits TNFSF14-LTβR interaction ameliorates tertiary lymphoid structures, damage-associated transitional epithelial cells, fibrosis, and emphysema, all of which can be post-acute sequelae of pneumonia." (PMID 41542776, 2026). "Still, little is known regarding the pathomechanistic role of TNFSF14 in virus-induced pneumonia." (PMID 41252214, 2026). "TNFSF14 drives the depletion of the TR-AM pool in IAV-induced pneumonia." (PMID 41252214, 2026).
acute respiratory distress syndrome (5 papers, 2020 to 2026). Progressive and life-threatening pulmonary distress in the absence of an underlying pulmonary condition, usually following major trauma or surgery. "With mainly neutrophilic expression and high abundance in the bronchoalveolar fluid of patients with severe virus-induced acute respiratory distress syndrome, TNFSF14 emerged as a key determinant of virus-driven lung injury." (PMID 41252214, 2026).
atopic dermatitis (5 papers, 2021 to 2025). "It was also shown that TNFSF14‐HVEM signalling in KCs promotes the development of atopic dermatitis–like skin inflammation induced by house dust mite allergens." (PMID 40768619, 2025). "The effects of TNFSF14 on KCs are being increasingly explored in inflammatory skin diseases, especially atopic dermatitis and PS, thereby revealing its pathological role in mediating KC proliferation, fibrosis accumulation, periosteal production, and inflammation." (PMID 40768619, 2025). "Additionally, TNFSF14‐HVEM signalling promotes inflammatory cytokine production and KC hyperplasia in atopic dermatitis." (PMID 40768619, 2025).
influenza (5 papers, 2024 to 2026). An acute viral infection of the respiratory tract, occurring in isolated cases, in epidemics, or in pandemics; it is caused by serologically different strains of viruses (influenzaviruses) designated A, B, and C, has a 3-day incubation period, and usually lasts for 3 to 10 days. "TNFSF14 deficiency or blockade preserved AMs during influenza infection and diminished bacterial burdens and mouse mortality during pneumococcal superinfection." (PMID 41542776, 2026). "During secondary pneumococcal infection of the influenza-infected lung, TNFSF14-deficient mice displayed significantly increased AM abundance, decreased bacterial burdens, mitigated weight loss, and improved survival." (PMID 41542776, 2026). "The observations that interrupting TNFSF14 or delivering LTβR-deficient AMs can be lifesaving during pneumococcal superinfection of influenza-infected mice suggest that AMs do something in these superinfected lungs that is profoundly helpful." (PMID 41542776, 2026). "Treatment with the neutralizing anti-TNFSF14 antibody led to a similar improvement in survival and weight loss, supporting the hypothesis that post-influenza TR-AM maintenance is key to survive secondary pneumococcal infection." (PMID 41252214, 2026). "Depletion of neutrophils reduced soluble TNFSF14 and rescued the AM population in influenza-infected mice, implicating neutrophil-derived TNFSF14 as triggering AM cell death." (PMID 41542776, 2026). "Deletion or blockade of TNFSF14 in mice decreased caspase activation and led to maintenance of the AM population during influenza infection." (PMID 41542776, 2026). "The intricate nature of TNFSF14-TNFRSF14-LTβR interactions thus points to a multitude of potential roles for the signaling axis in the context of influenza, besides TR-AM depletion." (PMID 41252214, 2026). "Single-cell RNA-Seq suggested neutrophils as sources of TNFSF14 in the infected mouse lung, and airspace neutrophils from patients with influenza ARDS had increased TNFSF14 expression." (PMID 41542776, 2026). "The ability of AMs to ingest and kill bacteria is plausibly an important role that is missing after TNFSF14-induced apoptosis, but many other phagocytes are also present in these influenza-infected lungs." (PMID 41542776, 2026). "Thus, TNFSF14 was sufficient for AM death, and both TNFSF14 and LTβR were necessary for the AM death observed during influenza infection." (PMID 41542776, 2026). "After identifying the TNFSF14/ LTβR pathway as mediating AM death during influenza infection, the authors asked whether the pathway contributes to bacterial superinfection severity." (PMID 41542776, 2026). "While both BCG and influenza vaccination were associated with lower relative concentrations of circulating inflammatory markers in men, it is important to recognise that the proteome profiles differ for the two vaccines, with some notable overlap (e.g. STAMBP and TNFSF14)." (PMID 40949320, 2025). "TNFSF14 treatment did not worsen virus-induced death in AECs, suggesting that TNFSF14 was not a strong driver of post-influenza distal epithelial cell apoptosis." (PMID 41252214, 2026).
liver fibrosis (5 papers, 2021 to 2025). "Our previous research found that splenectomy attenuated liver fibrosis by reducing the expression of LIGHT [Tumor necrosis factor superfamily 14 (TNFSF14; also known as LIGHT)]." (PMID 37021093, 2023). "TNFSF14, which acts downstream of RelB, promotes hepatic stellate cell activation and exacerbates liver fibrosis." (PMID 36313114, 2022). "Splenectomy has been shown to mitigate liver fibrosis; the effect may involve reduced systemic (serum) levels of LIGHT protein (aka TNFSF14), which promotes a JNK kinase-dependent reduction in TGFβ synthesis by liver macrophages." (PMID 41227335, 2025).
type 2 diabetes (5 papers, 2015 to 2025). "Additionally, TNFSF14 has been linked to immune-mediated destruction of β-cells in diabetic mice, and elevated levels of this cytokine have been observed in patients with type 2 diabetes." (PMID 40597598, 2025).
coronary artery disease (4 papers, 2023 to 2025). "Clinical observations have demonstrated that elevated levels of TNFSF14 may serve as an indicator of prospective clinical consequences in patients who have been diagnosed with stable coronary artery disease." (PMID 39734575, 2024). "While studies on ischemic stroke outcomes are lacking, increased TNFSF14 predicts major adverse cardiovascular events in patients with stable coronary artery disease, which is directionally concordant to what we observe here." (PMID 37794467, 2023).
preeclampsia (4 papers, 2019 to 2024). Preeclampsia is a hypertensive disorder of pregnancy that is characterized by new-onset hypertension with proteinuria presenting after 20 weeks of gestation, and depending on mild or severe forms may initially present with severe headache, visual disturbances, and hyperreflexia. "In women with preeclampsia, a serious hypertensive condition of pregnancy, an elevated level of circulating TNFSF14 has been detected." (PMID 32858953, 2020).